ENSG00000281348 (novel protein)
Gene: Protein-coding gene on chromosome 16 (29,817,239 to 29,830,627, forward strand). Ensembl gene ENSG00000281348.
Genetic constraint (gnomAD): Missense variants: 95 observed, 119.5 expected, observed/expected ratio (o/e) 0.79, 90% interval 0.67 to 0.94. Synonymous variants: 50 observed, 50.37 expected, observed/expected ratio (o/e) 0.99, 90% interval 0.79 to 1.26.